MBP (myelin basic protein)
Diseases named in the same sentence as MBP in open-access papers (continued):
Sharing a sentence is not in itself a finding about the gene and the disease.
experimental autoimmune encephalomyelitis (continued). "Application of MitoQ to experimental autoimmune encephalomyelitis (EAE), a mouse model of MS, demonstrated an increase in myelin basic protein (MBP) production and attenuation of neurodegeneration." (PMID 31354902, 2019). "Experimental autoimmune encephalomyelitis (EAE) can be induced by sensitization with CNS antigens, including myelin basic protein (MBP), myelin proteolipid protein (PLP), and myelin oligodendrocyte glycoprotein (MOG)." (PMID 30941144, 2019). "Three weeks after an acute phase of experimental autoimmune encephalomyelitis, CD49d+/CD154+ cells were found to be co-localized with O4+ cells (oligodendrocyte progenitors) in the areas of remyelination identified by myelin basic protein (MBP) labelling." (PMID 31861635, 2019). "We have introduced a B cell-/antibody-dependent model of experimental autoimmune encephalomyelitis (EAE), which is based upon active immunization of C57BL/6 (B6) mice with MP4, a fusion protein of myelin basic protein (MBP) and proteolipid protein (PLP)." (PMID 28738885, 2017). "GA was originally synthesized to resemble the structure of myelin basic protein (MBP) and was expected to provoke experimental autoimmune encephalomyelitis (EAE)." (PMID 28094337, 2017). "Previously, we showed that CD206-targeted liposomal delivery of co-encapsulated immunodominant myelin basic protein (MBP) sequences MBP46–62, MBP124–139 and MBP147–170 (Xemys) suppressed experimental autoimmune encephalomyelitis in dark Agouti rats." (PMID 27324388, 2016). "Here we used a peptide of myelin basic protein (MBP) and MBP-responsive TCR transgenic cells to show that PIT was capable of silencing Teff cells, thereby preventing murine experimental autoimmune encephalomyelitis (EAE)." (PMID 25546306, 2014). "This mixture of peptides was initially intended to mimic myelin basic protein (MBP) and to induce experimental autoimmune encephalomyelitis (EAE), the animal model of MS." (PMID 24134771, 2013). "For example, the MBP Tg mice raised in rigorous specific pathogen-free (SPF) conditions did not develop experimental autoimmune encephalomyelitis." (PMID 37830560, 2023). "The capacity of CD4+ T cells to induce CNS inflammation has, for example, been demonstrated in rodent experimental autoimmune encephalomyelitis (EAE) models, in which activated T cells recognizing myelin basic protein (MBP) are transferred into naïve rodents where they induce an MS-like disease." (PMID 37709997, 2023). "The most common experimental animal model for this disease is experimental autoimmune encephalomyelitis (EAE), which is induced by immunization with CNS tissue or myelin peptides, such as MOG, myelin basic protein (MBP), and proteolipid protein (PLP) in complete Freund’s adjuvant (CFA)." (PMID 35743229, 2022). "For instance, in experimental autoimmune encephalomyelitis, the total level of MBP is not changed but is instead restructured and aggregated." (PMID 34206635, 2021). "In mice, susceptibility to experimental autoimmune encephalomyelitis (EAE) decreases between the perinatal and adult period, which correlates with increasing age-dependent negative selection of MBP (myelin basic protein) specific T cells." (PMID 33968086, 2021). "It has recently been shown that myelin basic protein (MBP)-hydrolyzing and DNase activities are intrinsic properties of IgGs, IgMs, and IgAs from sera of MS and SLE patients, autoimmune SLE and experimental autoimmune encephalomyelitis (EAE) mice." (PMID 27196086, 2016). "For example, investigators who used an animal model of MS experimental autoimmune encephalomyelitis showed that rabbit T cells were reactive to both injected HBV polymerase peptide and myelin basic protein at the same amino acid, resulting in autoimmune demyelinating encephalomyelitis." (PMID 26582039, 2015).
experimental autoimmune encephalomyelitis (continued). "The experimental autoimmune encephalomyelitis (EAE) model, induced by immunizing animals with myelin-derived proteins (or polypeptides), such as myelin oligodendrocyte glycoprotein (MOG), proteolipid protein (PLP), and myelin basic protein (MBP), serves as a classic animal model of MS." (PMID 38243312, 2024). "The most commonly used model of CNS autoimmunity is experimental autoimmune encephalomyelitis (EAE): induction of cerebral and spinal inflammation by myelin autoantigens, such as myelin oligodendrocyte glycoprotein (MOG), proteolipid protein (PLP) and myelin basic protein (MBP)." (PMID 33108502, 2021).
Stroke (83 papers, 2009 to 2025). Sudden impairment of blood flow to a part of the brain due to occlusion or rupture of an artery to the brain. "Autoantibodies against myelin basic protein are associated with increased cognitive decline in the first year after stroke." (PMID 36495111, 2023). "The magnitude of lymphocyte TNF-α production in response to MBP during the acute phase of stroke was associated with poor stroke outcomes." (PMID 32719588, 2020). "Development of a Th1 response to myelin basic protein (MBP) is associated with worse neurological outcome 1 month after stroke." (PMID 31133816, 2019). "In a cohort of 58 stroke patients, elevated titers of serum antibodies to MBP were associated with cognitive decline in the year after stroke." (PMID 31001280, 2019). "In a study with 114 patients of ischemic stroke, a strong TH1 response to MBP at 90 days was associated with worse outcome and was more likely to develop in patients with severe stroke and post-stroke infection." (PMID 31001280, 2019). "There is evidence that TH1 type responses to MBP are associated with worse neurological outcome following experimental stroke." (PMID 31001280, 2019). "Examination of MBP showed loss in integrity and significant disorganization of the myelin sheaths in the WM, at the ipsilateral side, below the stroke point." (PMID 30283295, 2018). "Another survey by Shiue indicated that MBP was associated with the risk of stroke." (PMID 40438080, 2025). "The relationship between poorer neurological outcomes and systemic inflammation during stroke has also been highlighted, as patients who developed an infection following their stroke were more likely to have MBP and GFAP-specific T cells 3 months post-stroke; associated to a Th1 response." (PMID 33173502, 2020). "Both experimental and clinical studies evidenced that Th1 responses to MBP are associated with worse neurological outcome after stroke when infection occurred, and this kind of immune response could aggravate the neurologic deficits." (PMID 32719588, 2020). "Furthermore, they found that the Th1 response to MBP was an independent predictor of stroke outcome, and more robust cellular responses to MBP were associated with a decreased likelihood of a good outcome." (PMID 29422904, 2018). "In conclusion, oligodendrocytes and especially myelin-associated proteins such as the MBP were identified to react early after the ischemic event, and thus qualify as potential targets for both neuroprotective and regenerative approaches in stroke." (PMID 29467621, 2018). "Oral MBP tolerization induced TGF-β1 and the immunosuppressive features of this cytokine might underlie the beneficial effects of MBP tolerization in stroke." (PMID 25309322, 2014). "The increased expression of GFAP, VEGF, and MBP may help the brain to recover temporarily and offset its loss of function and thus may be the key to future treatment for patients who have experienced a stroke." (PMID 27597962, 2016). "The study also preliminarily uncovered that HDAC3-miKO decreased the MBP/SMI32 ratio 35 days after tFCI 30, leading us to further question how HDAC3 was implicated in the de-/re-myelination process after stroke." (PMID 39744685, 2025). "The results of protein and immuonfluorescence showed that the expression of MBP was decreased after stroke." (PMID 38511170, 2024). "In two studies, myelin basic protein, a protein that extravasates out of myelinated sheaths after damage, correlated with stroke location, specifically infarctions localized near white-matter tracts, and clinical stroke severity at admission." (PMID 37446092, 2023). "Ectopic MBP expression was detected around OLIG2+ cell bodies close to the injury in stroke animals." (PMID 37236198, 2023). "To study the overall distribution of axonal demyelination following stroke, we quantified the expression of MBP as a measure of myelin density." (PMID 37236198, 2023).
Stroke (continued). "To further assess the effect of DIO on white matter stroke remyelination, we measured peri-infarct myelin basic protein as a function of distance from the stroke core." (PMID 36543124, 2022). "After the onset of ischemic stroke, circulating type 1 T helper cells (Th1) react with brain-derived antigens (e.g., MBP), then aggravate brain injury, and worsen the prognosis of stroke." (PMID 36474712, 2022). "Researches in animal stroke models revealed that lymphocytes secrete transforming growth factor-β (TGF-β) in response to brain-derived antigens (like MBP)." (PMID 36474712, 2022). "MBP in the CST: A modest increase in MBP was observed in the stroke + CORT group (stroke FC = 0.8641 vs. stroke + CORT FC = 1.179, p < 0.05)." (PMID 34206635, 2021). "In the present study, we have determined axon myelination by quantifying CNPase+ oligodendrocytes and oligodendrocyte-produced MBP in the peri-infarct cortex 2 months after stroke." (PMID 33532129, 2021). "Recently, it was demonstrated that treatment with MTK in a mouse model of stroke increased expression of MBP, numbers of oligodendrocytes and fibre connectivity." (PMID 34769111, 2021). "Compared to the BF group, the MBP positive area of the BF+stroke group was smaller on both the contralateral (p = 0.02) and ipsilateral sides (p = 0.008) of stroke." (PMID 33187248, 2020). "The Stroke group also had a smaller MBP positive area than the BF group on the ipsilateral side (p = 0.04)." (PMID 33187248, 2020). "In summary, a small and transient neural-antigen specific inflammatory response by T cells was only observed against the myelin peptides coming from MBP protein in the acute phase of the stroke." (PMID 32719588, 2020). "We found that blood T lymphocytes from stroke patients were sensitized to myelin peptides of MBP on the day of admission." (PMID 32719588, 2020). "A previous study claimed that the activation of MBP-specific T cells in stroke was similar to that seen in multiple sclerosis." (PMID 32174916, 2020). "The MBP positive area of the stroke (Ips: 0.04 ± 0.01; Con: 0.08 ± 0.01) and BF+stroke (Ips: 0.05 ± 0.01; Con: 0.06 ± 0.01) groups were also smaller than the sham group on both sides of the basal ganglia (p < 0.001)." (PMID 33187248, 2020). "Previous studies showed increases of MBP antigens (along with neuron-specific enolase and S100-β) in the serum of stroke patients in the first 24 h after stroke." (PMID 32719588, 2020). "Higher peak concentrations of MBP, neuron-specific enolase (NSE) and S100B in the serum of patients at 24 h after stroke have been associated with stroke severity and larger infarct volumes." (PMID 31001280, 2019). "In a more recent study of the same group, which investigated autoimmune responses to MBP after stroke following immunization with MBP, again only 1/4–1/3 of the animals had a TH1 or TH17 response to MBP." (PMID 31001280, 2019). "IL‐2mAb treatment attenuated both MBP loss and SMI‐32 increase in the ischemic cortex and protected the integrity of the lateral corpus callosum at 7 days after stroke in dMCAO model." (PMID 30444079, 2019). "Animals that were sensitized to MBP prior to stroke had a sharply increased mortality within 24 h, whereas induction of oral tolerance to MBP resulted in significantly reduced infarct sizes at 24 h and 96 h after ischemia." (PMID 31001280, 2019). "At 7 and 14 days after stroke, we analyzed the expression level of white matter differentiation related markers (MBP, Olig2) and oligodendrocyte progenitor cell markers (CNPase, O4) in the lesion cortex of dMCAO mice." (PMID 30444079, 2019). "In stroke patients, neuronal glutamate receptor antigens and myelin basic protein fragments have been detected in CLNs60, suggesting communication between brain and CLNs." (PMID 31757960, 2019). "Modulation of immunity towards a Th1 phenotype is favoured during the inflammatory response to bacteria; Th1 responses to MBP, in particular, were more prevalent in stroke patients with pneumonia." (PMID 31281252, 2019).
Stroke (continued). "Shortly after stroke onset, brain-derived antigens (e.g., MBP, GFAP, CK-BB, NSE, and S100) were present within the peripheral circulation and cervical lymph nodes." (PMID 29422904, 2018). "An earlier reported, further translationally relevant fact is the measurable MBP in the cerebrospinal fluid of stroke patients." (PMID 29467621, 2018). "Twenty-four hours after experimental stroke, MBP-immunoreactivity robustly increased in ischemic regions with a gradual decline toward more peripheral areas." (PMID 29467621, 2018). "In the present study, qualitative analyses revealed a strong visually enhanced MBP-immunoreactivity in ischemia-affected areas 24 h after experimentally induced stroke." (PMID 29467621, 2018). "Thereby, the qualitative findings on an enhanced immunosignal for MBP at 24 h after experimental stroke were robustly confirmed by quantitative analyses with a maximum of reaction in the ischemic core and a declining course toward more peripheral areas." (PMID 29467621, 2018). "Biomarkers, including MBP, used for an acute diagnosis and management of stroke have been recently reviewed." (PMID 28890692, 2017). "We compared MBP expression between stroke untreated (n = 3) and Robot+BoNT (n = 4) groups 30 days after injury." (PMID 29280732, 2017). "One other very novel finding from this work is that both SI and stroke decreased the expression of myelin basic protein (MBP)." (PMID 27125783, 2016). "Our data suggest that the effects of isolation are even more detrimental than the effect of stroke on MBP expression." (PMID 27125783, 2016). "Ten-month-old stroke-free SHRSP had elevated MBP in one study of rats from the same colony in contrast to the present work." (PMID 24417612, 2014). "In humans, a pulmonary infection during the first 15 days after stroke increases the likelihood of developing Th1 response to MBP and GFAP." (PMID 25539803, 2014). "One possible explanation for this disparity is that induction of mucosal tolerance to MBP only hastens recovery from stroke, and that OVA tolerized animals "catch up" over time." (PMID 20142990, 2009). "Animals with a TH1(+) response to MBP in spleen, however, performed worse on the rotarod at 3 months after stroke onset." (PMID 20142990, 2009). "Indeed, our further investigation revealed that deletion of microglial HDAC3 decreased the SMI32/MBP ratio 35 days after stroke, which was highly correlated with the ameliorated sensorimotor behavioral outcomes." (PMID 39744685, 2025). "In the cell study, MBP expression levels were significantly higher in the oxygen and glucose deprivation and administration group.In summary, early exercise intervention after stroke can promote myelin repair by inhibiting the MEK/ERK signaling pathway." (PMID 38511170, 2024). "MBP is a marker for demyelination and is reduced after stroke." (PMID 37817190, 2023). "This measure of functional remyelination after stroke demonstrates reduced peri-infarct MBP+ immunoreactivity at 28 days post-stroke in DIO mice compared with control mice (p < 0.0001, two-way ANOVA, F = 3.11), indicating a failure of post-stroke remyelination." (PMID 36543124, 2022). "They demonstrated that their model successfully mimicked the ischaemic response as evidenced by the upregulated mRNA expressions of the key markers for stroke, S100B, IL-1β and MBP and additionally substantiate the role of transient cell-substrate interactions herein." (PMID 35806146, 2022). "Furthermore, microtubule-associated protein 2 (MAP2), NMDA receptor subunit NR-2A, myelin basic protein (MBP) and myelin oligodendrocyte glycoprotein were found in tonsils and cervical lymph nodes of patients with stroke." (PMID 34572077, 2021). "Additionally, the overall immunofluorescence of SMI32 increased in these three regions, resulting in a significant increase in the SMI32/MBP ratio in WT mice after stroke." (PMID 31226122, 2019).